H2AC16 (H2A clustered histone 16)
Description:
Core component of nucleosome. Nucleosomes wrap and compact DNA into chromatin, limiting DNA accessibility to the cellular machineries which require DNA as a template. Histones thereby play a central role in transcription regulation, DNA repair, DNA replication and chromosomal stability. DNA accessibility is regulated via a complex set of post-translational modifications of histones, also called histone code, and nucleosome remodeling.
Synonyms: H2AFI; HIST1H2AL; H2A/i; dJ193B12.9; H2A.i
Gene: Protein-coding gene on chromosome 6 (27,865,317 to 27,865,798, forward strand). Ensembl gene ENSG00000276903.
Subcellular location: Nucleus; Chromosome
Subcellular location (Human Protein Atlas): Nucleoplasm
Pathways (Reactome):
Chromatin organization: HATs acetylate histones; HDACs deacetylate histones; RMTs methylate histone arginines
Disease: Dengue Virus-Host Interactions; HCMV Early Events; HCMV Late Events
Metabolism of proteins: Metalloprotease DUBs; UCH proteinases; Ub-specific processing proteases
Gene Ontology:
Molecular function: enzyme binding; protein binding; structural constituent of chromatin; DNA binding; protein heterodimerization activity
Biological process: chromatin organization; heterochromatin formation
Cellular component: extracellular exosome; nucleoplasm; nucleosome; nucleus; chromosome
Genetic constraint (gnomAD): Loss-of-function variants: 12 observed, 7.71 expected, observed/expected ratio (o/e) 1.56, 90% interval 0.96 to 1.94. That is too few expected variants to judge how well the gene tolerates losing a copy. Missense variants: 212 observed, 187.29 expected, observed/expected ratio (o/e) 1.13, 90% interval 1.01 to 1.27. Synonymous variants: 131 observed, 83.54 expected, observed/expected ratio (o/e) 1.57, 90% interval 1.36 to 1.81.
Homologues: Orthologues: macaque H2AC11 (100% identical), macaque H2AC13 (100% identical), Drosophila melanogaster His2A:CG31618 (85% identical), Drosophila melanogaster His2A:CG33808 (85% identical), Drosophila melanogaster His2A:CG33814 (85% identical), Drosophila melanogaster His2A:CG33817 (85% identical), Drosophila melanogaster His2A:CG33820 (85% identical), Drosophila melanogaster His2A:CG33823 (85% identical), Drosophila melanogaster His2A:CG33826 (85% identical), Drosophila melanogaster His2A:CG33829 (85% identical), Drosophila melanogaster His2A:CG33832 (85% identical), Drosophila melanogaster His2A:CG33835 (85% identical), and 10 more. Paralogues in human: H2AC11 (100% identical), H2AC13 (100% identical), H2AC15 (100% identical), H2AC17 (100% identical), H2AC7 (99% identical), H2AC12 (98% identical), H2AC18 (98% identical), H2AC19 (98% identical), H2AC4 (98% identical), H2AC6 (98% identical), H2AC8 (98% identical), H2AC14 (98% identical), and 15 more.
Diseases named in the same sentence as H2AC16 in open-access papers:
H2AC16 is named in the same sentence as 6 diseases in open-access papers, as found by Europe PMC text mining. Sharing a sentence is not in itself a finding about the gene and the disease. The quoted sentences say what the papers report.
squamous cell carcinoma (1 paper, 2023). A carcinoma arising from squamous epithelial cells. "Of the histone genes that emerged from our analysis, H2AC16 was identified as a driver in two cancer types: squamous cell carcinoma and adenocarcinoma." (PMID 37444547, 2023).
immune disorder (1 paper, 2025). "H2AC16 expression demonstrated significant positive correlations with the MAPK signaling pathway and tyrosine metabolism, but negative correlations with drug metabolism and immune disorder-related pathways." (PMID 40703521, 2025).
H2AC16 also shares sentences with these, for which no sentence is quoted: systemic lupus erythematosus (2 papers); adenocarcinoma (1); Alcoholism (1); cancer (1).